MYG1 (MYG1 exonuclease)
Description:
3'-5' RNA exonuclease which cleaves in situ on specific transcripts in both nucleus and mitochondrion. Involved in regulating spatially segregated organellar RNA processing, acts as a coordinator of nucleo-mitochondrial crosstalk. In nucleolus, processes pre-ribosomal RNA involved in ribosome assembly and alters cytoplasmic translation. In mitochondrial matrix, processes 3'-termini of the mito-ribosomal and messenger RNAs and controls translation of mitochondrial proteins (Probable).
Synonyms: C12orf10; MYG; Gamm1; MST024; MSTP024
Tractability: PROTAC: ubiquitination databases record sites on it; its protein half-life has been measured.
Gene: Protein-coding gene on chromosome 12 (53,299,695 to 53,307,177, forward strand). Ensembl gene ENSG00000139637.
Subcellular location: Nucleus, nucleoplasm; Mitochondrion matrix; Nucleus, nucleolus
Subcellular location (Human Protein Atlas): Nucleoplasm
Gene Ontology:
Molecular function: 3'-5'-RNA exonuclease activity; protein binding
Biological process: mitochondrial RNA metabolic process; mRNA processing; rRNA processing
Cellular component: mitochondrial matrix; mitochondrion; nucleolus; nucleoplasm; nucleus; cytoplasm
Genetic constraint (gnomAD): Loss-of-function variants: 38 observed, 45.71 expected, observed/expected ratio (o/e) 0.83, 90% interval 0.64 to 1.09. The upper end of that interval is the gene's LOEUF score, 1.09, which puts it in group 4 of 6, group 1 being the genes least tolerant of losing a copy. Missense variants: 526 observed, 519.59 expected, observed/expected ratio (o/e) 1.01, 90% interval 0.94 to 1.09. Synonymous variants: 220 observed, 212.32 expected, observed/expected ratio (o/e) 1.04, 90% interval 0.93 to 1.16.
Homologues: Orthologues: chimpanzee MYG1 (99% identical), macaque MYG1 (96% identical), guinea pig MYG1 (89% identical), pig MYG1 (89% identical), rat Myg1 (87% identical), mouse Myg1 (86% identical), rabbit MYG1 (86% identical), dog MYG1 (79% identical), tropical clawed frog myg1 (56% identical), zebrafish myg1 (53% identical), Caenorhabditis elegans C27H6.8 (41% identical), Drosophila melanogaster CG11980 (40% identical).
Diseases named in the same sentence as MYG1 in open-access papers:
MYG1 is named in the same sentence as 9 diseases in open-access papers, as found by Europe PMC text mining. Sharing a sentence is not in itself a finding about the gene and the disease. The quoted sentences say what the papers report.
vitiligo (4 papers, 2010 to 2023). Generalized well circumscribed patches of leukoderma that are generally distributed over symmetric body locations and is due to autoimmune destruction of melanocytes. "Nine single nucleotide polymorphisms (SNPs) in the MYG1 locus were investigated by SNPlex assay and/or sequencing in vitiligo patients (n = 124) and controls (n = 325)." (PMID 20377893, 2010). "Our association analysis and expression studies suggest that MYG1 is one of the genes that in interaction with other genetic and environmental factors is responsible for the development of vitiligo." (PMID 20377893, 2010). "The purpose of the present study was to examine nine known SNPs in the MYG1 gene selected from the HapMap database and to study their associations with vitiligo susceptibility." (PMID 20377893, 2010). "We propose that the elevation of MYG1 expression in vitiligo can be both cause and effect depending on the case." (PMID 20377893, 2010). "Sequencing genomic DNA of 54 subjects (30 controls and 24 vitiligo patients) revealed that rs1534284/rs1534283 double-polymorphism is likewise prevalently monogenic in Estonian population with only Myg1 4Arg allele being present." (PMID 20377893, 2010). "According to growing evidence, the MYG1 gene is predominantly implicated in actively progressing vitiligo." (PMID 20377893, 2010). "Our aim was to examine nine known polymorphisms in the MYG1 gene, to investigate their functionality, and to study their association with vitiligo susceptibility." (PMID 20377893, 2010). "Mutations leading to overexpression of human MYG1 are associated with the autoimmune disorder vitiligo, suggesting that MYG1 may play some role in human innate immunity." (PMID 36888656, 2023). "Considering our present subjects, we cannot explain the relevance of our finding in vitiligo, but we propose that Myg1 has crucial functions inside mitochondria that may be implicated in vitiligo." (PMID 20377893, 2010). "Our study demonstrated that both MYG1 promoter polymorphism -119C/G and Arg4Gln polymorphism in the mitochondrial signal of Myg1 have a functional impact on the regulation of the MYG1 gene and promoter polymorphism (-119C/G) is related with suspectibility for actively progressing vitiligo." (PMID 20377893, 2010). "Vitiligo patients with -119G promoter have genetic inclination for higher expression and patients with less active promoter genotype harbour other genetic susceptibility loci, but MYG1 expression in their skin is still increased as a consequence of cellular changes that characterize vitiligo skin." (PMID 20377893, 2010). "Because our subjects were consistently homozygous for Myg1 4Arg allele, we cannot confirm the relevance of Myg1 Arg4Gln in vitiligo, but our results suggest that Myg1 has indispensable functions in the mitochondria and might be implicated in mitochondrial damage often present in vitiligo patients." (PMID 20377893, 2010). "Mitochondrial localization of Myg1 fits also with alternative theory of altered mitochondrial functionality of vitiligo patients." (PMID 20377893, 2010). "In general, MYG1 mRNA is elevated in both involved and uninvolved skin of vitiligo patients despite active or less active promoter genotype." (PMID 20377893, 2010). "Recently we have proposed a novel gene, MYG1 (Melanocyte proliferating gene 1) to be involved in vitiligo genetics." (PMID 20377893, 2010). "Further studies will be needed to explain the mechanisms of vitiligo pathogenesis and to understand the precise function of Myg1 in vitiligo." (PMID 20377893, 2010). "It is likely that part of the effect of increased MYG1 expression in vitiligo comes from higher prevalence of naturally more active -119G promoter carriers in vitiligo group." (PMID 20377893, 2010). "We have shown elevated expression of MYG1 mRNA in both uninvolved and involved skin in case of vitiligo." (PMID 20377893, 2010). "MYG1 mRNA expression is elevated in the skin of vitiligo patients." (PMID 20377893, 2010).
vitiligo (continued). "We recently showed that MYG1 mRNA expression is elevated in the skin of vitiligo patients." (PMID 20377893, 2010). "Therefore, alternatively: mitochondrially localized Myg1 can be involved in the regulation of altered metabolism and imbalance of antioxidants in vitiligo." (PMID 20377893, 2010). "The link between vitiligo and human 12q13 locus that includes MYG1 has been recently reported." (PMID 20377893, 2010). "The fact that MYG1 expression is elevated in both uninvolved and involved skin in case of vitiligo is in line with findings that melanocytes from normally pigmented skin of vitiligo patients also exhibit high susceptibility to chemical and physical oxidative stress." (PMID 20377893, 2010). "Minor allele -119G was related to higher MYG1 mRNA levels only in control group, but not in vitiligo group." (PMID 20377893, 2010). "Also, polymorphisms in the MYG1 gene were not related with concurrent autoimmune disease in vitiligo patients." (PMID 20377893, 2010). "However, up-regulation of several immune response-related genes after siRNA-mediated knockdown of MYG1 mRNA suggests that Myg1 may participate in pathways proposed by autoimmune theory of vitiligo pathogenesis." (PMID 20377893, 2010). "The precise function of Myg1 in the development of vitiligo is not clear." (PMID 20377893, 2010).
colon cancer (1 paper, 2025). "In colon cancer cells, melanocyte proliferating gene 1 (MYG1) facilitates the recruitment of the HSP90/GSK3β complex, thereby enhancing PKM2 stability and activity, which further amplifies aerobic glycolysis to drive tumor progression." (PMID 41169372, 2025).
leukoplakia (1 paper, 2022). A white patch or plaque on a mucous membrane that cannot be characterized clinically or pathologically as any other disease. "As a ubiquitously expressed and highly conserved factor, MYG1 is involved in immune regulation, which is not only associated with leukoplakia susceptibility, but also promoting the progression of lung adenocarcinoma and inhibiting autophagy." (PMID 35327947, 2022).
MYG1 also shares sentences with these, for which no sentence is quoted: colorectal cancer (2 papers); autoimmune disease (1); cancer (1); cerebral malaria (1); lung adenocarcinoma (1); tumor (1).